STAT3 (signal transducer and activator of transcription 3)
Diseases named in the same sentence as STAT3 in open-access papers (continued):
Sharing a sentence is not in itself a finding about the gene and the disease.
breast cancer (continued). "Our previous study found that SH003 targeted STAT3 in breast cancer cells." (PMID 29179443, 2017). "Tanshinone 1 can block STAT3 Tyr705 phosphorylation in MCF-7 breast cancer cells." (PMID 29207614, 2017). "To test whether Stat3 regulates centrosome clustering, we treated BT-549 and MDA-MB-231 human breast cancer cells with Stat3 short interfering RNAs (siRNAs) and counted the number of mitotic cells with declustered centrosomes." (PMID 28474672, 2017). "Human breast cancer cells express constitutively active STAT3." (PMID 27861147, 2017). "We also verified whether SH003 inhibits the STAT3 signaling pathway, leading to the suppression of breast cancer development and drug resistance." (PMID 28864784, 2017). "The autocrine hGH-stimulated EMT phenotypic conversion in breast cancer cells was reported to be partially mediated by signal transducer and activator of transcription 3 (STAT3) activation, which also mediated the oncogenicity of autocrine hGH in endometrial cancer cells." (PMID 28617312, 2017). "Here we investigated the role of miR-17-5p, which may repress the translation of the STAT3 oncogene, in the control of breast cancer cell apoptosis." (PMID 28178652, 2017). "STAT3 Y705 phosphorylation is uniformly reduced in MT/Shc2F/2F breast cancer cells." (PMID 28276425, 2017). "Conversely, the overexpression of HBXIP could rescue the inhibition caused by STAT3 knockdown in the cells treated with TNF-α, suggesting that TNF-α promotes the proliferation of breast cancer cells through STAT3/HBXIP signaling." (PMID 28938560, 2017). "We opted to further characterize the effect of FRK on STAT3 signaling in breast cancer cells." (PMID 29348886, 2017). "Notably, it has been demonstrated that CD44+ breast cancer stem cells had a relatively high level of STAT3 activation." (PMID 29036915, 2017). "Moreover, the silencing of P65 significantly inhibited the TNF-α-induced HBXIP promoter activities in the cells, suggesting that NF-κB-activated STAT3 is involved in the up-regulation of HBXIP induced by TNF-α in breast cancer cells." (PMID 28938560, 2017). "Moreover, it has been reported that OPN activates JAK2/STAT3 signaling and upregulates Bcl-2 and cyclinD1 in human breast cancer cells." (PMID 28505114, 2017). "Furthermore, STAT3-mediated tamoxifen resistance also has been shown in the CD44+/CD24−/low subpopulation of MCF-7 breast cancer stem cells characterized by their high mammosphere formation capacity." (PMID 29036915, 2017). "STAT3 signaling has been well characterized in breast cancer cells." (PMID 29348886, 2017). "In addition, a PHS treatment reduces the interaction of EGFR with the downstream JAK1/STAT3 signaling network in breast cancer cells." (PMID 29100426, 2017). "Moreover, in breast carcinoma cells, the STAT3 activation has been correlated with cell proliferation, in colon cancer STAT3 has been shown to be overexpressed, as well as in high-grade prostate cancer patients." (PMID 28709401, 2017). "Moreover, increased Stat3 expression and reduced miR-124 expression were associated with a poor response to radiotherapy in HER2-positive breast cancers." (PMID 27815936, 2016). "Together, these findings characterize LINC00520 as a lncRNA that is regulated by oncogenic Src, PIK3CA and STAT3, and which may contribute to the molecular etiology of breast cancer." (PMID 27626181, 2016). "Despite the fact that several experimental studies suggest that STAT1 and STAT3 play a critical role in breast cancer tumorigenesis, the prognostic value of these proteins in patients with breast cancer remains unclear." (PMID 27769057, 2016). "Constitutive activation of STAT3 was described in various types of cancers including breast cancer." (PMID 26888313, 2016). "Our study indicated that in breast cancer cells with conditioned medium from fibroblasts-breast cancer cells interaction, it could be found STAT3 activation, and down-regulation of EMMPRIN led to reducing STAT3 activation." (PMID 27325313, 2016).
breast cancer (continued). "Interleukin-6 could induced malignant transformation of stem cells in association with enhanced signaling of Stat331 and myeloid-derived cells endowed stem-like qualities to breast cancer cells through IL6/STAT3 and NO/NOTCH cross-talk signaling." (PMID 27833137, 2016). "The STAT3/5 status may induce changes in estrogen-responsiveness and the ERα-status of breast cancer cells, which is supported by the finding that STAT5 may regulate ERα." (PMID 27513743, 2016). "The results showed that HIF-1α could increase the percentage of breast cancer stem like cells via STAT3." (PMID 27325313, 2016). "To investigate whether inhibition of HER2 and STAT3 sensitizes HER2-positive SKBR3 breast cancer cells to irradiation, we used chemical inhibitors, lapatinib and S3I-201, that target HER2 and STAT3, respectively." (PMID 26755645, 2016). "To investigate whether Rhus coriaria affects the activation of STAT3 signaling in breast cancer cells, we analyzed the level of pSTAT3 in RCE-treated MDA-MB-231 cells." (PMID 26888313, 2016). "Interestingly, orthotopic tumours arising from transplantation of 4T1 murine mammary tumour cells exhibit both phosphorylated Stat3 and mCLCA5 expression." (PMID 27711075, 2016). "Deregulated STAT3 signaling has been associated with breast cancer and thus, alterations in PIAS3 may also play a role in breast cancer." (PMID 26768588, 2016). "To this end, when MCF7 breast cancer cells were treated with a STAT3 inhibitor or DMSO and radiated afterwards, we observed that the inactivation of STAT3 sharply attenuated the radiation-induced Notch2 (NICD2), Jagged1 and DLL4 mRNA expression and protein levels." (PMID 27462787, 2016). "Notably, expression of LINC00520 is increased in basal-like breast cancer cells, which also show a preferential increase in STAT3 activity." (PMID 27626181, 2016). "The goal of this study was to investigate the anticarcinogenic effects of polyphenol-enriched blueberry preparation (PEBP) on breast cancer stem cell development in cell models and in vivo, as well as to study the involvement of STAT3 and MAPKs signaling pathways in its chemopreventive activities." (PMID 26762586, 2016). "Irrespective, these results would indicate that STATs are central to the signaling networks in ductal breast cancer and that STAT3, in particular, has cross-talk with members of other pathways, such as the transcription factors HIF, and the nuclear factor kappa B." (PMID 27769057, 2016). "Nevertheless, it would suggest that the pleomorphic role of STAT3 in breast cancer prognosis, as an oncogene or a tumour suppressor, may be a function of the setting or cellular context, in particular the tumour microenvironment and necrosis." (PMID 27769057, 2016). "In addition to these malignancies, other cancers were reported to benefit from STAT3 in phenotype and prognosis as well, such as breast cancer, head and neck neoplasms, and brain tumor." (PMID 27577070, 2016). "In addition, IL-6 has been shown to be a direct regulator of the self-renewal of breast cancer stem cells as mediated by the IL-6 receptor/GP130 complex through STAT3 activation." (PMID 27462787, 2016). "Importantly, differential changes in SLC7A11 (xCT) mRNA levels were validated by RNA-sequencing, further confirming that STAT3/5 signaling is central to the transcriptional regulation of xCT in human breast cancer cells." (PMID 27513743, 2016). "We also found that EMMPRIN could down-regulate miR-106a and miR-106b expression in breast cancer cells, which led to activating STAT3 and enhancing HIF-1α expression." (PMID 27325313, 2016). "Findings reported here may be of therapeutic interest for clinically applying STAT3/5 inhibitors to target cancers in which xCT expression is up-regulated, including gliomas and aggressive breast cancers." (PMID 27513743, 2016).
breast cancer (continued). "Therefore, these particular STATs have emerged as pharmacological targets for cancer therapy, and the development of novel STAT3/5 inhibitors is of considerable clinical interest for treating breast cancer, glioma, and leukemia." (PMID 27513743, 2016). "Since IL-6/STAT3 is also an important mediator of the breast cancer cell-MDSC positive signaling loop, targeting key molecules in the IL-6/STAT3 pathways may be a promising therapy for recurrent and drug resistant breast cancers." (PMID 27609180, 2016). "Therefore, STAT3 activation is a key pathway for the survival of various resistant tumors, including breast cancer." (PMID 26755645, 2016). "Moreover, in breast cancer, leptin induces Src/Gbr2/Gab2/STAT3 activation and Rac-1 crosstalk to facilitate VEGF/VEGFR2 activation." (PMID 27472371, 2016). "In breast cancer, miR-29b expression is negatively associated with the HER2 sub-type, and its overexpression inhibits breast cancer cell proliferation and induces apoptosis mainly downregulating STAT3 protein levels." (PMID 27125250, 2016). "Finally, we defined the molecular basis of radiation-induced EMT in breast cancer cells, finding that it results from the fact that Notch2 upregulation is accompanied by IL-6-dependent STAT3 activation." (PMID 27462787, 2016). "Some factors secreted by ES cells could efficiently suppress Stat3 pathway activation in breast cancer cells, and were then involved in cancer cell growth, survival, invasion, and migration." (PMID 27460364, 2016). "The study indicated that EMMPRIN could down-regulate miR-106a/b which targets STAT3-HIF-1α to promote breast cancer cells showing stem-like cells and may play a fundamental role in regulation of CSC." (PMID 27325313, 2016). "Moreover, we uncovered the mechanism of Notch-driven EMT, in which Notch enhanced EMT through IL-6/JAK/STAT3 signaling axis in mammary tumor cells." (PMID 27462787, 2016). "Evidence is also accumulating for the important roles of Stat3 in breast cancer stem cells." (PMID 27460364, 2016). "However, other studies reported that overexpression of STAT3 was correlated with favorable outcome of patients with breast cancer, gastric cancer, lung cancer, colorectal cancer and melanoma." (PMID 26959884, 2016). "Interestingly STAT3 and c/EBPβ have overlapping consensus sequences in breast cancer promoters, suggesting competitive regulation." (PMID 27507046, 2016). "Using this approach, we found that exposure of breast cancer cells to the ES cell microenvironment resulted in reduced invasive potential, which might be mediated by Stat3 signaling inactivation." (PMID 27460364, 2016). "Moreover, it has been suggested that downstream pathways of HER2, such as PI3K/Akt and NF-kB, crosstalk with STAT3 signaling in resistant phenotypes of breast cancer." (PMID 26755645, 2016). "Furthermore, STAT3 has been shown to up-regulate tissue inhibitor of metalloproteinase-1 expression, which is recognised to reduce the invasiveness of breast cancer cells." (PMID 27769057, 2016). "CD44 also can interact with JAK2 and STAT3 to activate STAT3 in breast cancer." (PMID 27521216, 2016). "Interaction between STAT3 and Grim-19 is important for optimal function of mitochondrial complex I of electro transfer chain, which determines the appropriate amount of reactive oxygen species(ROS) to promote breast cancer growth." (PMID 27101310, 2016). "Furthermore, EBI3 blocking suppressed CRC cell proliferation through the gp130/Stat3 pathway, which mediated cell survival in various tumor, such as gastric cancer, breast cancer, hepatocellular carcinoma, and also CRC." (PMID 27247488, 2016). "In addition, leptin activation of STAT3 upregulates IL-1 and Notch in breast cancer and markers of cancer stem cells in pancreatic and breast cancer." (PMID 27472371, 2016).
breast cancer (continued). "The microenvironment of breast cancer cells plays a critical role in tumorigenesis and metastasis, which are closely related to activation of the signal transducer activator of transcription 3 (Stat3) signaling pathway." (PMID 27460364, 2016). "Moreover, several studies have shown that IL-6/STAT3 signaling is required for the growth of CD44+CD24− stem-cell-like breast cancer cells and for the dynamic equilibrium of breast CSCs." (PMID 27609180, 2016). "Our data provide evidence that the immunosuppression pathway genes STAT3,IL5, and GM-CSF may be novel susceptibility loci for breast cancer in women of European ancestry." (PMID 26621531, 2016). "Additionally, STAT3 has been reported to be overexpressed in nearly 40% of all breast carcinomas due, in part, to autocrine expression of IL-6." (PMID 27190500, 2016). "A variety of signal transduction pathways can activate Twist expression, including Wnt signaling, Akt, signal transducer and activator of transcription 3 (STAT3), and mitogen-activated protein kinases (MAPKs), which increase Twist protein levels in breast cancer cells." (PMID 26295469, 2015). "miR-20b leads to downregulation of VEGF in breast cancer cells in a STAT3 dependent manner." (PMID 26464811, 2015). "Ectopic expression of NDRG2 inhibits the tumor growth through inducing suppressor of cytokine signaling 1 and subsequent inactivation of signal transducer and activator of transcription 3 in breast cancer cells or by attenuating the AP-1 activity in colon carcinoma cells." (PMID 25889839, 2015). "Moreover, STAT3 has also been shown to play a role in the pathogenesis of breast cancer through its positive effects on invasion, stem cell expansion, and modulation of the environment." (PMID 26234940, 2015). "Indeed, constitutive activation of STAT3 has frequently been detected in diverse human cancer cell lines and tissues, including breast cancers." (PMID 26234940, 2015). "Moreover, we showed that elevated STAT3 signaling-mediated upregulation of MMP-2/9 is responsible for the enhanced invasive properties in SK-BR-3/EPR breast cancer cells." (PMID 26501276, 2015). "However, in EMT6 breast cancer cells, IL-22 induces STAT3 phosphorylation, but reduced ERK1/2 and Akt phosphorylation." (PMID 25793261, 2015). "A number of reports suggest that S-P STAT3 can contribute to tumor transformation and growth in several malignancies, including chronic lymphocytic leukemia, myeloproliferative neoplasms, prostate, and breast cancer." (PMID 26106584, 2015). "In addition, a previous study reported that the STAT3/c-Myc pathway mediated miR-16 suppression by progestin in mammary tumour cells 27, further supporting our conclusion." (PMID 25583328, 2015). "Specifically, we sought to determine whether constitutive STAT3 pathway activation could be responsible for primary resistance to trastuzumab in this breast cancer type." (PMID 26234940, 2015). "Our results suggest that it may be valuable to add agents targeting the STAT3 pathway to trastuzumab for treatment of HER2-positive breast cancer." (PMID 26234940, 2015). "Together, this suggests that the upstream regulation of STAT3 in breast cancer cells is complex and that the requirement of individual kinases may be dependent on cell state." (PMID 25699542, 2015). "MiR-519d functions as a tumor suppressor in breast cancer by suppressing STAT3 expression." (PMID 26631279, 2015). "Moreover, the increased IL-17 promotes the proliferation of the breast cancer line MDA-MB231 through the activation of STAT3." (PMID 25992978, 2015). "STAT3 is found to be constitutively phosphorylated to high levels in >50% of breast cancer derived cell lines, in >30% of breast adenocarcinomas and may be a poor prognostic indicator." (PMID 26464811, 2015).
breast cancer (continued). "In conclusion, we have used a proteomics approach to identify GRN as a novel STAT3-interacting protein that enhances STAT3 transcriptional activity and may play an important role in the pathophysiology of breast cancer." (PMID 26000098, 2015). "Moreover, miR-146b inhibits NF-κB-dependent production of IL-6, subsequent STAT3 activation, and IL-6/STAT3-driven invasion and migration in breast cancer cells." (PMID 26697428, 2015). "Together, this suggests that YB-1 is activated (pYB-1S102) by the STAT3 pathway (via various upstream pathways), which may represent a common feature among breast cancer cells." (PMID 26512918, 2015). "To determine whether extracellular PGRN had effects on STAT3 activity in tissue types besides breast cancer, we examined a STAT3-dependent luciferase reporter cell line derived from sarcoma cells." (PMID 26000098, 2015). "Here we report the use of a proteomics approach to identify a novel STAT3-interacting protein that modulates STAT3 activity and may play an important role in the pathophysiology of breast cancer." (PMID 26000098, 2015). "STAT3 has been shown to contribute to mammary gland tumor progression and metastasis in established mouse models, and activation of STAT3 has been detected in human breast cancer stem cell models." (PMID 26247733, 2015). "Strikingly, Shh signalling was predominantly activated in breast cancer cells in contact with stromal cells in response to chemotherapy, as well as Wnt, STAT3 and TGFβ pathways, which are involved in progenitor and stem cell renewal, metabolism, metastasis and chemoresistance." (PMID 25915429, 2015). "TFF3 has been demonstrated to promote STAT3 activity in the mammary carcinoma cells used herein." (PMID 26559818, 2015). "Moreover, NDRG2 expression negatively regulates JAK2/STAT3 through the regulation of the suppressor of cytokine signaling 1 gene in breast cancer cells." (PMID 25061501, 2014). "STAT3 is involved in human breast cancer with high STAT3 levels correlating with poorer survival." (PMID 24967588, 2014). "In fact, in line with this hypothesis, studies carried out in breast cancer and ovarian cancer cell lines have reported an inhibitory effect of salinomycin on surviving expression, dependent upon Stat3 inhibition." (PMID 24740347, 2014). "Recent studies have revealed the potential roles of STAT3 in breast cancer." (PMID 24297508, 2014). "Also, myeloid-derived suppressor cells isolated from patients with breast cancer express IDO1 in a STAT3-dependent manner." (PMID 24903009, 2014). "We wished to determine whether the co-expression of HER2 and ER induced STAT3 phosphorylation, and whether pSTAT3 promotes stem-like cell phenotype in the breast cancer model." (PMID 24297508, 2014). "However, inappropriate activation of STAT3 is a common event in a broad spectrum of human epithelial cancers, and there is evidence that both STAT5 and STAT3 can become activated in breast cancers." (PMID 24762632, 2014). "To evaluate the roles of STAT1 and STAT3 further, we used cell line models to study functional responses in endocrine sensitive and resistant breast cancer cells and then primary breast cancer samples to evaluate the associations between expression levels and clinical outcome." (PMID 24728078, 2014). "To test whether STAT3 drives the stem cell phenotype in breast cancer cells, we knocked down STAT3 gene by shRNAs and examined the CD44+ subpopulation by fluorescence activated cell sorting (FACS)." (PMID 24297508, 2014). "STAT3 has been shown to be constitutively activated in 35% to 60% of breast cancers." (PMID 24886617, 2014). "Furthermore, Stat3 is widely expressed in breast cancer and orally bioavailable small-molecule inhibitor of Stat3 can regress human breast cancer xenografts, suggesting that Stat3 is a potential therapeutic target for breast cancer." (PMID 24416452, 2014).